HRAS (HRas proto-oncogene, GTPase)
Diseases named in the same sentence as HRAS in open-access papers (continued):
Sharing a sentence is not in itself a finding about the gene and the disease.
breast cancer (continued). "LncRNA LIPE-AS1 was co-expressed with 5 ferroptosis-related genes (HRAS, PHKG2, MAPK14, EGLN2, and GPX4), including 4 ferroptosis driver and 1 ferroptosis suppressor, and we found that LIPE-AS1 was a protective factor for breast cancer patients’ prognosis." (PMID 34164433, 2021). "THSWD could regulated the RNA and protein expression of core targets HRAS, MAPK1, AKT1, GRB2, and MAPK14 for treatment of breast cancer." (PMID 34513708, 2021). "Interestingly, NRAS and HRAS result to be overexpressed in basal-like and HER2 tumors, the most aggressive subtypes of breast cancer." (PMID 31781501, 2019). "The active mutants of HRAS, KRAS, and NRAS were found in a subset of breast cancers." (PMID 30111373, 2018). "Our observations also evoke BCL-2/HRAS interactions and their reported effects on de-differentiation of luminal breast cancer cells, by mechanisms that have not been totally described yet29." (PMID 29066722, 2017). "This is exemplified by the identification of a fusion gene involving HRAS in the model and the lack of such fusion genes in primary breast cancer." (PMID 27512948, 2016). "An in‐frame HRAS fusion gene was identified in a head and neck primary tumour (RNH1–HRAS) that leads to increased levels of HRAS expression 66; however, no additional HRAS fusion genes were detected in primary breast cancers." (PMID 27512948, 2016). "Four known biomarkers (CHEK2 in both plasma and urine, CDKN1B, PCNA, and THBS1) were identified as false positives (red) in our breast cancer list, and seven (KRAS, GDNF in both breastmilk and plasma, MYCL1 in both blood and serum, CD40LG, CGA, CTAG1A, ERCC6, and HRAS) in our lung cancer list." (PMID 25379168, 2014). "Among the recurrently amplified and deleted loci, we noted that canonical oncogenes, such as EGFR and HRAS, were recurrently amplified in CMTs; however, amplification of ERBB2 and MYC, which is common in human breast cancers, was not reflected in the GISTIC peaks of CMTs." (PMID 32680987, 2020).
melanoma (129 papers, 2005 to 2026). A malignant, usually aggressive tumor composed of atypical, neoplastic melanocytes. "In the literature, both KRAS and HRAS mutations have been reported in approximately ~2% of melanomas." (PMID 41142596, 2025). "TRPML1 exhibits high expression in various cancer types, including melanoma, pancreatic ductal carcinoma, triple negative breast cancer, and cancer cells bearing oncogenic HRAS mutations." (PMID 38802335, 2024). "Further, KRAS is mutated in pancreatic and lung cancer, NRAS in melanoma and HRAS in oral and skin SCC." (PMID 38963974, 2024). "Oncogenic mutations in BRAF, NRAS HRAS genes have been described commonly in melanomas of skin and other sites, however, the same at this site has been conspicuously absent." (PMID 38509523, 2024). "Class 3 BRAF mutations and NF1 loss were common in various HRAS-mutant cancers, in particular melanomas." (PMID 37503077, 2023). "Specifically, nevus spilus can also be caused by variants in HRAS, but HRAS is a rare driver of melanoma and is less frequently found mutated in melanoma than PTPN11." (PMID 36566878, 2023). "The prevalence of co-altered mutations in the MAPK pathway in melanomas was the highest among the cancer types we analyzed and was 61.1% for HRAS, 59.4% for KRAS, and 31.3% for NRAS-mutant tumors." (PMID 37503077, 2023). "HRAS mutations are present in only 1.5% of all melanoma cases, and elevated HRAS expression is correlated with shorter survival in patients with cutaneous melanomas." (PMID 35954441, 2022). "A growing of literature has documented that the NRAS mutation is substantially related to a higher incidence of melanoma (i.e., 15–30% of melanoma), which is ten times higher than repeatedly than HRAS or KRAS." (PMID 36551688, 2022). "Nevertheless, the projected number of new melanoma cases with KRAS/HRAS mutations is substantial and is around 2600 persons per year." (PMID 34831002, 2021). "NRAS is preferentially mutated in melanoma and acute myeloid leukaemias, while HRAS mutations are rare." (PMID 33562401, 2021). "Mutations in KRAS and HRAS occur at a low frequency in melanomas, occurring at 1.7% and 1.9%, respectively." (PMID 34831002, 2021). "This is supported by the observation of a significantly higher incidence of coexisting KRAS/NRAS/HRAS mutations in melanomas with class-3 mutations." (PMID 31277584, 2019). "HRAS mutations were detected in 9 melanomas including 2 with p.G13 N (c.37_38delinsAA) resulting from a CC > TT (or GG > AA) alteration, a signature of UV-damage." (PMID 31277584, 2019). "For example, mutations in KRAS are common in lung, colon, and pancreatic cancers, those in NRAS predominate in melanoma, and HRAS mutations are commonly seen in bladder, head and neck, and skin cancers." (PMID 29349077, 2017). "Although mutations in KRAS (2%) and HRAS (1%) have been observed in melanoma specimens, NRAS is the most commonly mutated Ras family member (15~20%) among the three closely related classical Ras proteins." (PMID 26993606, 2016). "HRAS overexpression causes melanoma in mice and melanocyte-specific expression of oncogenic HRAS has been shown to induce melanoma in zebrafish." (PMID 27689402, 2016). "Several studies have reported the presence of HRAS mutations in spitzoid tumors with benign behavior, and absence in clear-cut spitzoid melanomas." (PMID 25593912, 2014). "Additionally, the specificity of mutations in melanoma for NRAS compared to HRAS and KRAS is noteworthy, thinking that all three isoforms proceed in GIMM and melanoma-related short-term cultures." (PMID 36551688, 2022). "HRAS mutations are very common in cancer and G12D variant is primarily found in bladder urothelial carcinoma, cutaneous melanoma, infiltrating renal pelvis, ureter urothelial carcinoma, melanoma, and colorectal adenocarcinoma." (PMID 36458814, 2022). "Interestingly, TYRP1 mRNA levels in cells carrying mutation either in NRAS or in HRAS were much higher than in BRAFV600E melanoma cells." (PMID 31624899, 2020).
melanoma (continued). "Kirsten rat sarcoma viral oncogene homolog (KRAS)and Harvey rat sarcoma viral oncogene homolog (HRAS) may also be mutated in melanoma, but only in a very small percentage of cases (~1%)." (PMID 30987166, 2019). "Thus, HRAS rs112587690 represents an additional susceptibility factor for the development of melanoma." (PMID 22618666, 2012). "Thus, HRAS rs12628 represents a strong susceptibility factor for the development of melanoma." (PMID 22618666, 2012). "A zebrafish melanoma model has previously been established in which the melanocyte-specific promoter microphthalmia-associated transcription factor a (mitfa) is used to drive oncogenic human HRas (HRasG12V, hereafter referred to as V12RAS) expression in melanocytes." (PMID 21179501, 2010). "The interplay between NRAS, KRAS and HRAS in the context of NRAS-mutant melanoma and other tumor types remains poorly understood." (PMID 40473796, 2025). "NRAS mutations are present in approximately 20% of human melanomas, whereas HRAS and KRAS mutations occur in only 1% and 2% of melanomas, respectively." (PMID 40076927, 2025). "Activating mutations in either of the three RAS isoforms (HRAS, KRAS, or NRAS) are found in nearly 20% of all human tumors with NRAS mutated in ~25% of melanomas." (PMID 39379700, 2024). "The OFA has been specifically designed to provide comprehensive genomic profiling of solid tumors and includes the mutational study of melanoma-related genes such as BRAF, NRAS, KIT, MAP2K1, or HRAS." (PMID 39000050, 2024). "Of all RAS isoforms (HRAS, KRAS, and NRAS in humans), the most common mutation in melanomas occurs in the NRAS gene, while in other types of human cancers, mutations are more frequent in the KRAS gene." (PMID 39770908, 2024). "For example, CDKN2A and BAP1 germline mutations predispose melanoma and mesothelioma, while CDKN2A and HRAS were frequently mutated in vulvar squamous cell carcinoma." (PMID 37626750, 2023). "Amongst HRAS-mutant melanomas, 42% carried a co-altered NF1 mutation, significantly greater than in KRAS-/NRAS-mutant melanoma and other HRAS-mutant cancers (p<0.05)." (PMID 37503077, 2023). "As the mitogen-activated protein kinase (BRAF-MAPK) signaling pathway is frequently activated in melanoma, we analyzed TERT in melanoma subtypes with hotspot mutations in BRAF, RAS (NRAS, KRAS, HRAS) and NF1 genes in the SKCM cohort." (PMID 37418389, 2023). "Inactivation of NF1 increases HRAS, KRAS, and CRAF activities in mutated melanoma cells (BRAFV600E), restoring ERK activation even in the presence of BRAFi." (PMID 36286442, 2022). "The melanoma cell line used in our experiments also carries a mutation upstream of ERK1/2, affecting HRAS and NRAS genes." (PMID 35563794, 2022). "In opposition, variants in HRAS (HRas proto-oncogene, GTPase) and KRAS (KRAS proto-oncogene, GTPase) are less common: 2% and 3%, respectively, of all melanoma." (PMID 36614156, 2022). "Oncogenic mutations in RAS genes (KRAS, NRAS, and HRAS) or RAF genes (RAF-1, BRAF, and A-RAF) occur in many cancer types, including the melanoma cells." (PMID 34822435, 2021). "Activating HRAS mutations are found in approximately 20% of Spitzoid neoplasms, while BRAF and NRAS mutations are mostly found in conventional melanomas." (PMID 33100226, 2020). "RAS proteins (KRAS, NRAS and HRAS) are frequently activated in different cancer types (e.g., non-small cell lung cancer, colorectal cancer, melanoma and bladder cancer)." (PMID 33187149, 2020). "KRAS is often altered in pancreatic carcinoma, colorectal tumors and lung malignancies and HRAS mutations are common in dermatological malignancies and head and neck cancers whereas NRAS alterations in melanomas and in hematopoietic malignancies." (PMID 31681616, 2019).
melanoma (continued). "Mutations in HRAS can be found in dermatological malignancies and head and neck cancers, while NRAS mutations are common in melanomas and in some hematopoietic malignancies." (PMID 31681616, 2019). "BRAF and NRAS-mutated melanomas showed a significantly lower incidence of coexisting mutations of different genes (10 and 8.1%, respectively) as compared to PIK3CA, HRAS and KIT-mutated melanomas (75, 67 and 36%; all P < .001)." (PMID 31277584, 2019). "NRAS (22%) and HRAS (9%) isoforms are less frequently mutated with melanomas accounting for half of NRAS mutant patients, while head and neck cancer and bladder cancer together account for half of HRAS mutant patients." (PMID 30287508, 2018). "Our studies with zebrafish embryos, overexpressing human HRAS G12V in melanocytes and developing melanoma at one month of age, show that this model can be used to assess the effects of TpeL in vivo." (PMID 29662661, 2018). "In humans, of these family members, malignant melanomas predominantly bear NRAS mutations with only very rare KRAS and HRAS mutations." (PMID 30188888, 2018). "Mutations in HRAS are most frequently found in melanoma, bladder and mammary carcinoma; NRAS mutations are found in melanoma and thyroid carcinoma; and KRAS mutations are most prevalent in cancers of the bladder, ovary, thyroid, lung, colon and pancreas." (PMID 27096871, 2016). "The development of keratoacanthoma and cutaneous squamous-cell carcinomas in melanoma patients treated with the selective BRAF inhibitor vemurafenib has been linked to the presence of frequent mutations in RAS, particularly HRAS." (PMID 27999416, 2016). "To further elucidate the role of CIP2A we transiently downregulated the protein in four melanoma cell lines harboring the common genetic mutations BRAFV600E (WM983b), BRAFV600E/PTENnull (WM9), NRASQ61K (1366) and the less frequently seen HRAS mutation (FEMX1)." (PMID 25663244, 2015). "In melanomas, the MAPK pathway is frequently hyperactivated by mutations in the BRAF gene (approximately 50% of melanomas) but also in NRAS (18%), KIT (9%), HRAS (2%) or KRAS (2%) genes (COSMIC database)." (PMID 26098773, 2015). "Overall, melanoma metastases from patients carrying rs12628 CC genotype trended toward higher HRAS mRNA expression, followed by those from patients carrying TT and TC genotypes, respectively." (PMID 22618666, 2012). "This included the melanoma driver mutations NRAS Q61K/R, BRAF V600E, CDKN2A P114L, and HRAS G13." (PMID 40075679, 2025). "Arguably, rapid detection of mutated genes using IHC allows attending clinicians to rationally select targeted therapies for neoplasms known to harbor HRAS, NRAS or KRAS p.Q61R mutations including ameloblastoma, melanoma, colorectal, urothelial and thyroid cancers, among others." (PMID 37901104, 2023). "KRAS or HRAS mutations are detected infrequently in approximately 5% of melanoma patients, whereas NRAS mutations (NRASmut) are found in about 25% of patients, which makes NRAS the second most frequent mutation type after BRAF in melanoma." (PMID 36551302, 2022). "NRAS, HRAS and KRAS isoforms are mutated in 15–20%, 2% and 2% of melanomas, respectively." (PMID 36286442, 2022). "Targeting KRAS and HRAS mutations in melanomas is not currently being pursued due to the lack of insight on the biological impact in melanomagenesis." (PMID 34831002, 2021). "The most prevalent significantly mutated genes in melanoma such as BRAF, NRAS, KRAS, HRAS, and NF1 were also explored; the results indicated that the high-FRGs score group have lower mutation frequencies in NRAS, KRAS, and NF1 compared to the low-FRGs score group." (PMID 34745259, 2021). "It should be noted that melanomas rarely harbor KRAS mutations and more often HRAS mutations." (PMID 34437586, 2021). "For instance, HRAS G12V expression in melanoma inhibits apoptosis." (PMID 32620824, 2020).
melanoma (continued). "In addition to HRAS and KRAS, we also computationally identified several significantly mutated genetic interactions for new gene families, such as SEPT1-BRIP1 in melanoma." (PMID 32101536, 2020). "In this study BRAF, NRAS, KRAS, HRAS, PIK3CA and KIT mutations were examined in melanomas." (PMID 31277584, 2019). "Moreover, JMJD6 expression levels are higher in the samples with HRAS and BRAF mutations compared to samples with wild type HRAS and BRAF, suggesting that JMJD6 is upregulated by RAS signaling in these melanomas." (PMID 30619488, 2018). "Also, oncogenic NRAS and HRAS increase GLI1 function in melanoma cells, and HH-GLI signaling is required for NRAS-induced mouse melanoma growth." (PMID 30158435, 2018). "Although it is not clear why NRAS mutations are more frequent in melanoma compared to HRAS or KRAS mutations, there is evidence that NRAS is overexpressed in melanocytes relative to other RAS isoforms." (PMID 29349077, 2017). "Finally, other less frequently mutated melanoma genes (KRAS, HRAS, KIT, GNAQ, GNA11) were enriched in tumors wild‐type for BRAF, NRAS, and NF1." (PMID 28267273, 2017). "Spitz tumors generally lack mutations in oncogenes classically associated with melanoma, such as NRAS, KIT, GNAQ, and GNA11, though distinct histopathologic forms have been found to harbor BRAFV600E and HRAS mutations, and suggest a role for activating kinase pathways in tumorigenesis." (PMID 28895885, 2017). "The role of RAS in melanoma development was investigated through the melanocyte-specific expression of mutated HRAS: tyrosinase-driven expression of HRasV12G in mouse melanocytes failed to induce melanoma development." (PMID 29156643, 2017). "Although NRAS mutations have been reported in 14% of human melanoma cell lines and 15–25% of melanoma clinical specimens, nevertheless, HRAS and KRAS mutations are not common in melanoma." (PMID 25695059, 2015). "First, this model shows that expression of oncogenic HRAS can initiate and maintain melanoma formation without the need for inactivating mutations in tumor suppressors as reported for other (zebrafish and mouse) models of melanoma." (PMID 21170325, 2010). "Furthermore, executing a transitive search for the Uberon terms by using the Property Paths function, we identified 14 melanoma-related genes (e.g., HRAS and PTEN), and 12 anatomical parts in which these genes were expressed, such as the “skin of limb” as an example." (PMID 40380154, 2025). "Meningeal melanocytomas and melanomas do not usually harbor HRAS, KRAS, BRAF, or KIT mutations." (PMID 39061148, 2024). "In addition, class 3 BRAF mutations were more prevalent in HRAS-mutant salivary gland (5%), and bladder (9%), and melanoma (11%) cancers, whereas none were present in the respective KRAS- and NRAS-mutant tumors (p<0.05 for all)." (PMID 37503077, 2023). "These opposite results may reflect distinct effects of TRPML on different cancer cells that could be due to distinctive mutations, for example HRAS signaling is mutated in head and neck cancer cells but not in melanoma cells." (PMID 32411610, 2020). "In these samples, a concomitant mutation in HRAS gene (p.Gly12Asp) was identified, confirming the association between inactivating BRAF mutations and the stimulation of the Raf-MEK-ERK pathway by other effectors, as a mutated RAS protein, in a molecular subtype of melanomas." (PMID 31547467, 2019). "However, the strong oncogenic activity of HRAS-G12V, which is even able to induce melanoma without the need of coadjuvating mutations in tumor suppressors, results in a similar tumor burden in wild type and Spint1a-deficient fish at later stages." (PMID 31519199, 2019).